KLF4 (KLF transcription factor 4)
Diseases named in the same sentence as KLF4 in open-access papers (continued):
Sharing a sentence is not in itself a finding about the gene and the disease.
aneurysm (10 papers, 2016 to 2025). Bulging or ballooning in an area of an artery secondary to arterial wall weakening. "In turn, KLF4 has been identified as a critical determinant in VSMC phenotypic switching in aneurysm formation." (PMID 40100302, 2025). "Specifically, KLF-4 is upregulated by shear stress, a typical EC differentiation stimulus found during aneurysm formation, and inhibits SMC maturation." (PMID 35563123, 2022). "The synthetic phenotype of vSMCs plays a crucial role in progressive aneurysm formation in human and is associated with high expression of VEGF-A, vimentin, KLF-4, and ECM degrading enzymes." (PMID 35563123, 2022). "Stress‐ and immunogenic‐induced TC cell proliferation and therefore increased exosome release of soluble stem cell factors such as PDGF‐A and KLF‐4 may initiate an incessant cascade of remodelling steps in aneurysm pathology." (PMID 34562312, 2021). "The expression inhibition of KLF4 could benefit for preventing aneurysm formation, and miR-145 can effectively inhibit KLF4 protein expression." (PMID 31320641, 2019). "We hypothesized that Klf4, Klf2, and Zfp148 are important for phenotypic modulation and one mechanism of phenotypic modulation during aneurysm formation is by the activation of autophagy." (PMID 31025534, 2019). "Furthermore, they found that the key driver of this phenotype switch appeared to be a large increase in Klf4 expression and VSMC-specific Klf4 knockout largely prevented aneurysm development in this model." (PMID 35463756, 2022). "In summary, these studies represent only one possible mechanism for Klf4, Klf2, and Zfp148 as activators of autophagy during AAA formation and lead further credence to the importance of autophagy, Klf4, Klf2, and Zfp148 in broad significance for the overall aneurysm phenotype." (PMID 31025534, 2019).
heart failure (10 papers, 2016 to 2025). Inability of the heart to pump blood at an adequate rate to meet tissue metabolic requirements. "KLF4 knockout is associated with mitochondrial dysfunction, myocardial fibrosis, and even heart failure." (PMID 39206261, 2024). "Another knock- out study showed that cardiac-specific deletion of the Klf4 gene significantly increased mice susceptibility to heart failure and death following pressure overload induced by TAC." (PMID 37569355, 2023). "Another KLF family transcription factor, KLF4, regulates oxidative phosphorylation in mitochondria in concert with ERR, and cardiomyocyte-specific KLF4-deficient mice develop heart failure." (PMID 35055179, 2022). "It has been reported that cardiomyocyte-specific Klf4 knock-out mice display an exaggerated expression of cardiac foetal genes after induced cardiac hyperthrophy and the endothelial Klf4 is up-regulated after the loss of cerebral cavernous malformation signalling, which results in heart failure." (PMID 26979619, 2016). "Klf4, Gas6, and Tsc22d3 showed consistent up-regulation at all timepoints studied post-MI in the adult mouse heart, and in both types of heart failure in human patients." (PMID 36082978, 2023). "As well as Klf4, Klf6, and Klf9 showed an enriched expression in cells from patients with heart failure compared with the healthy human heart." (PMID 36082978, 2023). "CCM complex disruption in the endocardium modulates the MEKK3‐MEK5‐ERK5 axis to upregulate Klf4 and Klf2 expression resulting in mid‐gestation heart failure." (PMID 26612856, 2016). "However, based on the results of our present experiments, we propose a hypothesis that KLF4 may play a role in regulating inflammatory responses in cardiomyocytes and alleviating heart failure by downregulating the expression levels of inflammatory factors." (PMID 40042137, 2025). "In mammals, the regulation of autophagy by KLFs, including KLF2, KLF4 and KLF6, is also involved in vascular aging, heart failure, and cell aging." (PMID 37543362, 2023).
Hyperglycemia (10 papers, 2021 to 2025). An increased concentration of glucose in the blood. "C1q/tumor necrosis factor-related protein 9 (CTRP9), an emerging potential cardiokine, contributes to the inhibition of hyperglycemia-induced endothelial senescence through an AMPKα/ Krüppel-like factor 4 (KLF4)-dependent signaling pathway." (PMID 36077539, 2022). "In conclusion, our present study provided the first evidence that hyperglycemia accelerates endothelial senescence by influencing the expression of KLF4 and its downstream signaling targets." (PMID 34744738, 2021). "Recent studies show that hyperglycemia activates DNA methyltransferases (DNMTs), inducing hypermethylation of anti-inflammatory gene promoters (e.g., KLF4) and perpetuating inflammation, suggesting that glycemic control may modulate plaque phenotypes through epigenetic mechanisms." (PMID 41169883, 2025). "Such experiment revealed that inhibition of H3K4me3 catalysis in intermittent hyperglycemia-challenged EC normalized KLF2 level without reversing the level of KLF4." (PMID 35392173, 2022). "Data from the current study support the hypothesis that incubation of HUVECs in HG medium, as a model of hyperglycemia, promotes HUVEC senescence by increasing the expression of the KLF4 protein and downstream signaling targets." (PMID 34744738, 2021).
oral squamous cell carcinoma (10 papers, 2010 to 2025). "Burkitt lymphoma and oral squamous cell carcinoma (OSCC) present another subtype where KLF4’s onco-suppressive role has been recently demonstrated." (PMID 41463190, 2025). "Another study reported the role of KLF4 in oral squamous cell carcinoma, in which mechanisms of action were described as both tumour suppressors and oncogenes." (PMID 37559082, 2023). "Expression of LINC-ROR has been reported to be upregulated in undifferentiated oral squamous cell carcinoma and correlated with the overexpression of KLF4, C-MYC, OCT4, and SOX2." (PMID 33745265, 2021). "In this study, we investigated KLF4 expression and KLF4 promoter methylation in oral squamous cell carcinoma (OSCC) cell lines and in primary OSCC tissues." (PMID 26517087, 2015). "However, the roles of KLF4 in oral squamous cell carcinoma remain unclear." (PMID 26517087, 2015).
aortic aneurysm (9 papers, 2019 to 2025). A ruptured aneurysm located in the wall of the proximal portion of the descending aorta proceeding from the arch of the aorta. "Others have established that KLF4 is a potent repressor of the mature contractile phenotype and that KLF4 depletion in SMC results in a reduction in atherosclerotic plaque burden as well as aortic aneurysm formation." (PMID 37991018, 2023). "Thus, PDGF‐A and KLF‐4 seem to play a critical role in aortic aneurysm formation via induction of pathological phenotype switching of SMCs and also lead to altered extracellular matrix composition." (PMID 34562312, 2021). "Thus, KLF4 is an important player in aortic aneurysm morphogenesis by regulating VSMC phenotypic switching." (PMID 31623405, 2019). "Using single-cell RNA sequencing, the authors identified novel markers of smooth muscle cell phenotype modulation during aortic aneurysm development, including enhanced TGF-β signaling and Kruppel-like factor 4 (Klf4) overexpression, confirming their observations of the Fbn1C1041G/+ MFS mouse model." (PMID 35008861, 2021).
Burkitt lymphoma (9 papers, 2015 to 2025). A rare form of malignant mature B-cell non-Hodgkin lymphoma. "By overexpressing KLF4 in Burkitt lymphoma cell lines, researchers were able to induce cell cycle arrest in Go and G1, pausing the proliferation of B cells." (PMID 40831570, 2025). "In Burkitt lymphoma (BL), KLF4 acts as a tumor suppressor by reducing MYC expression and its downstream target EZH2 while activating tumor suppressors such as TXNIP." (PMID 39995670, 2025). "In another study, KLF4 is shown to inhibit B cell proliferation in patients with B cell lymphomas, like Burkitt Lymphoma, follicular lymphoma, and classic Hodgkin lymphoma." (PMID 40831570, 2025). "In an in vitro model using a cell line derived from Burkitt lymphoma (Ramos), we showed high expression of KLF4 and YY1, and the KLF4 promoter contained two consensus sites for YY1 binding." (PMID 31040909, 2019). "In any event, our finding that KLF4 expression is sufficient to induce lytic EBV gene expression in Burkitt lymphoma cell lines indicates that KLF4 can promote lytic EBV gene expression outside the context of epithelial cell differentiation." (PMID 26431332, 2015). "Burkitt lymphoma is another subtype where KLF4 oncosuppressive role has been recently demonstrated." (PMID 39135777, 2024). "Nevertheless, overexpression of KLF4 in both the Raji and Jijoye latently infected, EBV-positive, Burkitt lymphoma cell lines was sufficient to induce the expression of the EBV immediate-early proteins, Z and R, as well as the early lytic protein, BMRF1." (PMID 26431332, 2015). "Interestingly, KLF4 also has a strong regulatory effect on the MSC/ABF-1 repressor, which is highly expressed in classic Hodgkin’s Lymphoma, follicular lymphoma, and Burkitt Lymphoma." (PMID 40831570, 2025). "In contrast, KLF4 protein is not detectably expressed in B cells, where EBV normally enters latent infection, although KLF4 over-expression is sufficient to induce lytic EBV reactivation in Burkitt lymphoma cells." (PMID 26431332, 2015).
coronary artery disease (9 papers, 2017 to 2025). "Evidence from human genetics further underscores the relevance of KLF4, as genome-wide association studies have implicated it as a susceptibility locus for coronary artery disease." (PMID 41307849, 2025). "Klf4 was subsequently identified as a coronary artery disease genome-wide association study (GWAS) variant." (PMID 38258907, 2024). "Adding translational significance was the identification of Klf4 by genome-wide association studies (GWAS) in human populations as a coronary artery disease risk locus." (PMID 37991018, 2023). "In particular relevance, our in vivo ChIPseq analyses on chromatin from mouse atherosclerotic arteries demonstrated that 39% of accepted human coronary artery disease (CAD) genome-wide association study (GWAS) loci are the nearest gene binding targets of KLF4 or OCT4 specifically in SMC." (PMID 37942066, 2023). "Klf4 and Oct4 control opposite patterns of gene expression in late-stage atherosclerotic lesions and may regulate genes associated with human coronary artery disease (CAD) risk." (PMID 32674599, 2020). "Moreover, our lab recently showed that loss of Klf4 in SMC resulted in a marked reduction of mRNA transcripts associated with cellular senescence and inflammation, including > 40 putative KLF4 target genes previously identified as coronary artery disease GWAS variants." (PMID 38258907, 2024). "For example, our RNA-seq analyses demonstrated that inhibition of HIF-1α in DF-treated ECs rescued the expression of anti-inflammatory molecules KLF2, KLF4, and PPAP2B (a coronary arterial disease candidate gene identified by genome-wide association studies)." (PMID 28556776, 2017).
lymphoma (9 papers, 2017 to 2025). A malignant (clonal) proliferation of B- lymphocytes or T- lymphocytes which involves the lymph nodes, bone marrow and/or extranodal sites. "KLF4 shows a bifunctional role in hematological malignancies, even though we and other authors have shown an oncogenic role in MM, pediatric lymphoma, and NHL cell lines." (PMID 33412518, 2021). "Recent studies by our group have shown that the expression of the KLF4 in lymphoma plays a pro-tumoral role and that it correlates with malignancy." (PMID 33194748, 2020). "Our results clearly show the constitutive expression of KLF4, strongly suggesting the importance of KLF4 protein expression in the pathogenesis of lymphoma." (PMID 31040909, 2019). "Recently, we have shown that KLF4 is expressed in pediatric lymphomas, and this expression is higher in the subtype Burkitt and correlates with a poor prognosis and low patient survival." (PMID 31040909, 2019). "The results indicated that a total of 69% of follicular lymphomas expressed KLF4, and 88% of DLBCL lymphomas expressed KLF4." (PMID 31040909, 2019). "To corroborate our results in vitro, we evaluated YY1 and KLF4 expression in patients with lymphoma." (PMID 31040909, 2019). "Epigenetic inhibition of KLF4 in B-cell lymphomas and particularly in classic Hodgkin lymphoma cases increases lymphoma survival and decreases apoptosis." (PMID 29848383, 2018). "Together the results indicate that miR-7 expression plays a role in the migration capacity and chemoresistance, by regulating specific targets such as YY1 and KLF4, where these have previously been reported by our working group and others, have a role in the malignancy of lymphoma." (PMID 33194748, 2020). "Likewise, our working group and other groups have reported that the transcription factor YY1 is expressed in high levels in lymphomas, and we recently reported that this transcription factor regulates the expression of KLF4 in lymphoma cell lines." (PMID 33194748, 2020). "This is the first report describing a correlation between KLF4 and YY1 expression in lymphoma, and this study identifies KLF4 and YY1 as potential disease markers, which could be considered biomarkers at the time of diagnosis for predicting disease behavior." (PMID 31040909, 2019). "The regulatory mechanism underlying KLF4 expression in cancer, and specifically in lymphoma, is still not understood." (PMID 31040909, 2019). "In addition, studies in lymphoma have demonstrated the transcriptional regulation of KLF4 by YY1." (PMID 33412518, 2021). "We also propose that the use of pharmacological or chemical inhibitors targeting YY1 and KLF4 could be an alternative treatment for patients with lymphoma that are known to be positive for YY1 and KLF4 expression, thus offering a therapeutic alternative for this disease." (PMID 31040909, 2019). "In conclusion, our findings demonstrate for the first time that YY1 regulates transcriptional KLF4, and inhibiting YY1 expression directly affects KLF4 expression in lymphoma." (PMID 31040909, 2019). "Based on independent findings regarding the expression of KLF4 and YY1 in lymphomas, we proposed that there is a correlation between these proteins." (PMID 31040909, 2019). "The participation of miR-7 in the pathogenesis of lymphoma, including its role in the regulation of transcription factors that establish more aggressive patterns of lymphoma, such as KLF4 and YY1, as well as its importance in lymphoma, has not been defined." (PMID 33194748, 2020). "Furthermore, YY1 expression and KLF4 are increased in patients with lymphoma, and high expression of YY1 correlates with KLF4." (PMID 31040909, 2019). "Interestingly, we found a positive correlation between the expression of KLF4 and YY1 in several data sets analyzed from the lymphoma study by Campagno." (PMID 31040909, 2019). "We analyzed the expression of KLF4 and YY1 for each subtype of lymphoma included in the TMA." (PMID 31040909, 2019).
lymphoma (continued). "In previous work reported by us and other authors KLF4 and YY1 independent expression does not depend on the subtype of lymphoma; however, patient samples showed a correlation as described by us and other authors." (PMID 31040909, 2019).
myeloma (9 papers, 2015 to 2023). "To further investigate the potential relevance of a KLF4-associated autophagy component in MM, we identified KLF4 profile neighbors across 304 MM patient samples in the Multiple Myeloma Research Consortium reference collection dataset (GEO accession number GSE26760)." (PMID 26109433, 2015). "Stemness-associated transcription factors, such as Sox2, Oct3/4, Nanog, Klf4, β-catenin and c-Myc, play major roles in the maintenance of myeloma stem cell-like SP cells in MM78,79." (PMID 36289430, 2022). "This task can be achieved with the transcription factors, octamer-binding transcription factor 4 (Oct4), Krüppel-like factor 4 (Klf4), Sex determining region Y-box2 (Sox2) and oncogene of myelomatosis (c-Myc) (OKSM), which have been recognized for preserving the pluripotency of a staminal cell." (PMID 33217903, 2020). "TFs like KLF4 and IRF8 were up-regulated in osteocytes co-cultured with myeloma cells in comparison with osteocytes cultured alone." (PMID 27405725, 2016). "In conclusion, a total of 393 DEGs were identified between osteocytes co-cultured with and without myeloma cells, and KLF4, IRF8, EGF, EGR1, S1PR1, C3AR1, and NPY1R might be involved in osteocyte cell apoptosis induced by MM cells." (PMID 27405725, 2016).
skin cancer (9 papers, 2010 to 2023). "KLF4 loss leads to increased tumor cell growth in skin cancer." (PMID 37854069, 2023). "KLF4, in skin cancer and BC, appears to promote tumour progression, suggesting that KLF4 is an oncogene in these tumours." (PMID 35177016, 2022). "On the other hand, KLF4 is a tumor suppressor in a UVB-induced mouse skin tumor model and its expression is decreased in samples from patients with SCC and basal cell carcinoma of the skin." (PMID 34570823, 2021). "Consistently, the expression of Slug was positively correlated with the expression of CSC markers such as CD44, NANOG, ALDH1A1 and KLF4 in skin cancer." (PMID 27901498, 2017). "An Oncomine database analysis also demonstrated that VEGF-C expression was positively correlated with the expression of some CSC markers, such as OCT4, KLF4, NANOG, CD44, CD34 and CD133, suggesting that VEGF-C increases the CSC features of skin cancer cells." (PMID 27901498, 2017). "In skin cancer cells, LOXL2 is recruited by KLF transcription factor 4 (KLF4) to the notch receptor 1 (NOTCH1) promoter, where it decreases H3K4me3 levels, thereby impairing RNA polymerase II recruitment and inhibiting NOTCH1 transcription, thus repressing epidermal differentiation." (PMID 37762708, 2023). "Therefore, we examined whether VEGF-C affects cancer stemness in skin cancer cells and found that knockdown of VEGF-C significantly decreased the expression of the CSC markers SOX2, OCT4, KLF4, NANOG, CD133, CD34 and CD44 as well as ALDH activity, which is a hallmark of CSCs." (PMID 27901498, 2017).